LRRK2 (leucine rich repeat kinase 2)
Diseases named in the same sentence as LRRK2 in open-access papers (continued):
Sharing a sentence is not in itself a finding about the gene and the disease.
systemic lupus erythematosus (12 papers, 2017 to 2025). An autoimmune multi-organ disease typically associated with vasculopathy and autoantibody production. "Hub gene LRRK2 was identified as being associated with increased risk of systemic lupus erythematosus." (PMID 38137330, 2023). "LRRK2 deficiency largely attenuates the pathogenic progress of lupus-like features in pristane-induced mice." (PMID 30670047, 2019). "Altogether, our results indicate that LRRK2 deficiency exhibits the protection against pristane-induced lupus-like pathology, partially owing to less production of total IgG and autoantibodies." (PMID 30670047, 2019). "Another study has also pointed to a genetic association between LRRK2 and susceptibility to systemic lupus erythematosus (SLE)." (PMID 32256311, 2020). "A significantly positive correlation was apparent between LRRK2 expression in B cells and system lupus erythematosus disease activity index (SLEDAI), an indicator for disease severity." (PMID 30670047, 2019). "A pristane-induced lupus-like mouse model was used to explore the effects of LRRK2 on the development of SLE." (PMID 30670047, 2019). "More significantly, LRRK2 expression in B cells was positively correlated with system lupus erythematosus disease activity index (SLEDAI), an indicator for disease severity, and serum IgG levels in SLE patients." (PMID 30670047, 2019). "LRRK2 promoted B cell maturation and hyper-activation, increased autoantibody production and aggravated pristane-induced lupus in a SLE animal model, thus implicating LRRK2 as a new regulator of B cell function and humoral immunity." (PMID 30670047, 2019). "LRRK2 protein was also significantly increased in neutrophils from PD patients, while LRRK2 mRNA transcription was increased in B cells from patients with systemic lupus erythematosus (SLE), and in macrophages and dendritic cells localized in inflamed intestinal tissue biopsies from CD patients." (PMID 32210756, 2020). "Although Lrrk2−/− mice exhibit normal B cell development and function at the steady state, whether pristane treatment induces different lupus-like phenotypes is worthy of investigation." (PMID 30670047, 2019).
thyroid cancer (12 papers, 2015 to 2025). "In recent years, several studies have identified LRRK2 mutations or dysregulation of its expression in various types of human malignancies including thyroid cancer, intrahepatic cholangiocarcinoma, lung cancer, and renal carcinoma." (PMID 39744510, 2025). "However, a contradictory study showed that LRRK2 gene amplification causes a certain types of cancers, such as papillary renal and thyroid cancers." (PMID 26384650, 2015). "In addition, LRRK2 amplification has been implicated in renal and thyroid carcinomas." (PMID 29568677, 2018). "The depletion of LRRK2 inhibited cell proliferation and migration and induced thyroid cancer cell apoptosis by inhibiting the c-Jun N-terminal kinase signaling pathway." (PMID 36499051, 2022). "The effect of LRRK2 on thyroid cancer progression was determined by series in vivo and in vitro experiments." (PMID 36253446, 2022). "knocked down LRRK2 and found that silencing LRRK2 suppresses thyroid cancer cell growth by facilitating apoptosis and cell‐cycle arrest." (PMID 33784003, 2021). "In cancer research, a recent study has demonstrated the role of LRRK2 only in thyroid cancer." (PMID 36499051, 2022). "Knockdown of LRRK2 significantly suppressed the growth of thyroid cancer cell in vitro and in vivo." (PMID 36253446, 2022). "This LRRK2 was shown to participate in host immune responses involving the recruitment of macrophages in the tumor microenvironment, and its overexpression was reported in kidney and thyroid cancers." (PMID 36499051, 2022). "In addition, LRRK2 promotes tumor cell growth and survival in papillary renal and in thyroid carcinomas and proliferation together with metastatic capacity in intrahepatic cholangiocarcinoma cells." (PMID 36051080, 2022). "Article also reported that LRRK2 is overexpressed in thyroid cancer." (PMID 33784003, 2021). "Notably, LRRK2 amplification has been observed to be of indirect oncogenic potential in papillary renal cell carcinoma and thyroid carcinomas trough MET signaling." (PMID 32722212, 2020). "LRRK2 was amplified and overexpressed in papillary renal and thyroid carcinomas in the study." (PMID 32196072, 2020). "Two thyroid cancer cell lines, BCPAP and KHM-5M were transfected with siRNA targeting LRRK2, and the knockdown efficiency were confirmed by qPCR and Western blot." (PMID 36253446, 2022). "No incidents of lung, bladder, kidney, or thyroid cancers were reported in the LRRK2 group." (PMID 29568677, 2018).
lung carcinoma (11 papers, 2015 to 2025). "In a recent study, loss of LRRK2 was observed to promote carcinogen-induced lung tumorigenesis in both patient and mouse lung cancer models." (PMID 36986550, 2023). "The present study identified and validated NUF2, KIF4A, KIF18B, DLGAP5, NEK2, and LRRK2 as promising diagnostic biomarkers for lung cancer." (PMID 36499051, 2022). "Here, NUF2, KIF4A, and KIF18B were commonly upregulated, and LRRK2 was commonly downregulated in both lung cancer subtypes." (PMID 36499051, 2022). "For the first time, we propose NUF2, KIF4A, KIF18B, DLGAP5, NEK2, and LRRK2 as biomarkers for lung cancer progression." (PMID 36499051, 2022). "In a carcinogen-induced murine lung cancer model, multiplex IHC confirmed that LRRK2 was expressed in alveolar type II (AT2) cells, a main LUAD cell-of-origin, while its loss perturbed AT2 cell morphology." (PMID 33483550, 2021). "Likewise, our study has highlighted the significance of LRRK2 in lung cancer; however, the effect of LRRK2 inhibitors in the cancer context requires further clarification." (PMID 36499051, 2022). "Therefore, the differential expression of LRRK2 in tumor versus normal tissues must be validated with a larger sample size to accurately discern its regulatory role in lung cancer." (PMID 36499051, 2022). "Hub genes including LRRK2, BMI1, MNDA (myeloid cell nuclear differentiation antigen), OTX1, FFAR2, and PITX1 play a significant role in lung cancer progression." (PMID 38137330, 2023).
tuberculosis (11 papers, 2010 to 2025). A chronic, recurrent infection caused by the bacterium Mycobacterium tuberculosis. "When mice missing the gene equivalent to LRRK2 were infected with the bacterium that causes tuberculosis, they experienced more severe disease." (PMID 32057291, 2020). "The integrated GWAS, Hi-C, eQTL, ChIP-Seq, and ATAC-Seq analysis identify the long-range target genes of mycobacterial disease-susceptible SNPs and identify LRRK2 as a potential drug target, whose inhibitor AdoCbl has an anti-tuberculosis effect both in vitro and in vivo." (PMID 36195603, 2022). "Given that LRRK2 is also associated with infections of the lung such as tuberculosis (discussed later in this review), it appears that LRRK2 expression, perhaps specifically LRRK2 kinase activity, may be crucial for immunity in the lung." (PMID 32508566, 2020). "In the GSE20050, we found that when compared with normal lung parenchyma, LRRK2 was significantly down-regulated in caseous tuberculosis granulomas (p = 0.0361), but CCR7 and FYN was upregulated (p = 0.0024 and p = 0.0486, respectively)." (PMID 32987825, 2020). "Among these, the SNP rs1873613 is located in the anchor of a dynamic chromatin loop with LRRK2, whose inhibitor AdoCbl could be an anti-tuberculosis drug candidate." (PMID 36195603, 2022). "Importantly, these data uncover LRRK2 as a regulator of the early clearance of Mtb, suggesting the kinase activity of LRRK2 can be a potential target for host‐directed therapies in tuberculosis." (PMID 29789389, 2018). "The pathway terms appearing in both LRRK2 and PINK1 enrichment results are “tuberculosis”, “viral myocarditis”, and “IL-17 signalling pathway”, although mainly not among the statistically significant results after adjustment for multiple hypothesis testing." (PMID 40650986, 2025).
multiple sclerosis (10 papers, 2018 to 2025). A progressive autoimmune disorder affecting the central nervous system resulting in demyelination. "Interestingly, LINGO2 is a member of LRR gene family that, along with LRRK2, has been linked to Essential tremor (ET) and PD and has even become a promising therapeutic target in multiple sclerosis (MS) and PD." (PMID 33493177, 2021). "Moreover, we showed that treatment of LRRK2-mutant flies with fingolimod, a drug that is currently being used to treat multiple sclerosis, ameliorates their disease-associated phenotypes but otherwise has no apparent effects on the climbing performance of control flies." (PMID 31664682, 2020). "There was an overlap between PD and inflammatory diseases, including rheumatoid arthritis and multiple sclerosis, in 17 novel loci, including LRRK2." (PMID 33584195, 2021). "In the Norwegian LRRK2 families there has been a significantly higher incidence of inflammatory diseases like multiple sclerosis and rheumatoid arthritis that seen in other PD populations." (PMID 33584195, 2021). "A combination of PD and multiple sclerosis (MS) may be due to the immune function of LRRK2 and its interrelation with α-synuclein." (PMID 40243562, 2025). "A possible relationship between multiple sclerosis (MS) and LRRK2 PD has also been suggested." (PMID 39175765, 2024). "Methodology of selection of a LRRK2 inhibitor effective in OPC proliferation, differentiation, and in a murine model of multiple sclerosis." (PMID 38287523, 2024).
multiple system atrophy (10 papers, 2008 to 2025). Multiple system atrophy (MSA) is a neurodegenerative disorder characterized by autonomic failure (cardiovascular and/or urinary), parkinsonism, cerebellar impairment and corticospinal signs with a median survival of 6-9 years. "Pathogenic variants in LRRK2 were found to be extremely rare in multiple system atrophy (MSA), progressive supranuclear palsy, and corticobasal degeneration." (PMID 34630269, 2021). "The genetic basis of Multiple System Atrophy involves a complex interplay of various genetic factors, prominently featuring the SNCA gene, LRRK2 mutations, GBA mutations, COQ2 expression alterations, and abnormalities in the MAPT gene." (PMID 40291849, 2025). "Neuropathology in LRRK2 p.I2020T mutations from the original Sagamihara family also revealed heterogeneous pathologies, including pure degeneration of the SNpc without any inclusions, Lewy bodies, or multiple system atrophy (MSA) pathology." (PMID 30333048, 2018).
diabetes (9 papers, 2008 to 2025). "9% (30 of 342) of patients with LRRK2-associated PD had diabetes mellitus, which was unexpectedly high and might be due to the effect of multiple-comparison testing." (PMID 18539534, 2008). "MYH9, ERBB2, TCF4, VIM (vimentin), LRRK2 and CAV1 have been implicated as a principal mediator of diabetes mellitus." (PMID 36837510, 2023). "Overexpression of LRRK2 in diabetes has been demonstrated in a rat model, leading to greater fragmentation of mitochondrial organelles." (PMID 30861027, 2019). "By analyzing the protein-protein interaction (PPI) and coexpression networks of the transcriptomes of different groups, it is inferred that Lrrk2 and Irak3 may be pharmacodynamic genes for type 2 diabetes mellitus (T2DM)." (PMID 32351607, 2020). "Several components of the thioredoxin system are closely linked to LRRK2, including PRDX3, TXNIP, and TXNRD1, which have been identified in recent years as risk factors for obesity and diabetes in human subjects, and as nutrient sensing mechanisms and controlling factors of adipogenesis in mice." (PMID 23799078, 2013). "Emerging multimodal biomarkers, genetic risk (e.g., APOE4, LRRK2, TREM2), metabolic status (insulin resistance, diabetes), imaging (amyloid/tau PET, MRI), and fluid omics (CSF proteomics, metabolomics), could be integrated into companion-diagnostic frameworks as in oncology." (PMID 41226780, 2025). "Studies have shown that hub genes including LRRK2 and FFAR2 have been reported to be correlated with prognosis in a diabetes mellitus." (PMID 38137330, 2023).
Dystonia (9 papers, 2008 to 2024). An abnormally increased muscular tone that causes fixed abnormal postures. "G2019S LRRK2 carriers are three times more susceptible to early-onset dystonia compared to idiopathic PD patients, and DBS appears be beneficial for them." (PMID 39199492, 2024). "Multiple studies have described the presence of painful dystonia in different cohorts of LRRK2 pathogenic variant carriers." (PMID 38020640, 2023). "Dystonia, especially painful off-period foot dystonia, is more common in LRRK2 mutation carriers after starting dopaminergic treatment." (PMID 35754954, 2022). "Although this dystonia was nearly three times more probable in the first 2 years of the disease, it was seen only rarely in patients with LRRK2 Gly2019Ser-associated PD before dopamine-replacement treatment." (PMID 18539534, 2008). "This distinguishes LRRK2 Gly2019Ser-associated PD from PD due to recessive genes, in which pretreatment dystonia can be prominent." (PMID 18539534, 2008). "Dystonia occurred during the first 2 years of the disease in 22 of 126 patients (18%) with mutations in LRRK2 compared with 5 of 21 (4%) of patients with idiopathic PD (OR 4·5, 95% CI 2·4–8·4; p<0·0001)." (PMID 18539534, 2008). "Atypical examples of dystonia that affected the arm (n=2), neck (n=2), tongue (n=1), and that caused blepharospasm (n=4) were also reported in patients with mutations in LRRK2." (PMID 18539534, 2008). "Any form of dystonia was seen in 126 of 301 patients (42%) with mutations in LRRK2 compared with 121 of 487 patients (25%) with idiopathic PD; in most patients this was a painful “off period” foot dystonia." (PMID 18539534, 2008). "Patients with LRRK2 Gly2019Ser-associated PD had a greater propensity to dystonia than did patients with idiopathic PD." (PMID 18539534, 2008). "Only one patient with a mutation in LRRK2 had dystonia before dopamine-replacement treatment." (PMID 18539534, 2008). "Furthermore, dystonia is the most specific feature that characterizes LRRK2 G2019S carriers in our series with an ODDS ratio of 4.65." (PMID 28465860, 2017). "Notably, a case report documented a patient with severe and painful ON-dystonia who carried a LRRK2 N1437H variant which is not recognized among the established pathogenic variants." (PMID 38020640, 2023).
ovarian carcinoma (8 papers, 2012 to 2025). A malignant neoplasm originating from the surface ovarian epithelium. "High LRRK2 expression has also been associated with poorer survival in ovarian cancer." (PMID 35247252, 2022). "High expression of LRRK2 is associated with poor survival of ovarian cancer patients." (PMID 33784003, 2021). "Moreover, LRRK2 inhibition or depletion increases the susceptibility of ovarian cancer cells to Olaparib in vitro and in vivo." (PMID 33784003, 2021). "This imbalance leads to reduced expression of the miR-205 target LRRK2 and enhances the proliferative, migration, and invasion of ovarian cancer cells." (PMID 39744510, 2025). "In clinical specimens, LRRK2 high expression is high related with advanced clinical characteristics and poor survival of ovarian cancer patients." (PMID 33784003, 2021). "In our study, GSK2578215A sensitization to PARP is detectable only for ovarian cancer cell lines with LRRK2 overexpression." (PMID 33784003, 2021). "All these findings indicate ovarian cancers expressing high levels of LRRK2 are more resistant to treatment potentially through promoting HR." (PMID 33784003, 2021). "Thus, the LINC01133/miR-205/LRRK2 axis represents a novel pathway driving ovarian cancer pathogenesis." (PMID 39744510, 2025). "GSK2578215A is an LRRK2 inhibitor that could affect the sensitivity of ovarian cancer treatment by suppressing homologous recombination." (PMID 39588117, 2024). "Our study identifies LRRK2 as a new target that potentially regulates HR in ovarian cancer cells." (PMID 33784003, 2021). "LRRK2 has not previously been implicated in ovarian cancer development but analyses of The Cancer Genome Atlas (TCGA) data suggests ~3% of primary HGSOCs harbor somatic mutations in this gene." (PMID 24070420, 2013). "LRRK2 inhibitor GSK2578215A suppresses HR and sensitizes ovarian cancer cells to PARP inhibitor." (PMID 33784003, 2021). "Therefore, decreased LRRK2 expression by miR-205 results in the JNK pathway inactivation and the apoptosis inhibition of ovarian cancer cell." (PMID 34721577, 2021). "Furthermore, combination treatment with an LRRK2 and PARP inhibitor may be a novel strategy to improve the effectiveness of LRRK2 expression ovarian cancers." (PMID 33784003, 2021).
sleep disorder (8 papers, 2008 to 2025). A change from the patient's baseline sleeping pattern, in the hours slept and/or an alteration/dysfunction in the stages of sleep. "Genetically, mutations of the leucine-rich repeat kinase 2 (LRRK2) gene associated with sleep disorders and PD were significantly decreased when melatonin was administered." (PMID 35668933, 2022). "Mutations of the leucine-rich repeat kinase 2 (LRRK2) gene are associated with pronounced sleep disorders or cognitive dysfunction in neurodegenerative diseases." (PMID 36138936, 2022). "However, it remains blurred with regards to the effects of LRRK2 deficiency on sleep disorders and cognition loss, and the underlying mechanisms." (PMID 36138936, 2022). "Based on the clinical similarities between IPD and LRRK2-PD we hypothesized that those sleep disorders occurring in IPD may also be present in LRRK2-PD." (PMID 26177462, 2015). "In summary, our findings show that sleep disorders in LRRK2-PD are common." (PMID 26177462, 2015). "In NMC, EDS was rarely reported and RBD was absent, suggesting that these sleep disorders are not premotor markers of LRRK2-PD." (PMID 26177462, 2015). "The study of sleep disorders therefore does not seem to be useful to distinguishNMC who are in the premotor stage of LRRK2-PD and are likely to develop PD during lifetime." (PMID 26177462, 2015).
Anosmia (7 papers, 2008 to 2024). An inability to perceive odors. "The PPMI study also includes a prodromal arm (P-PPMI) in which subjects with RBD, anosmia or a mutation (LRRK2, GBA or SNCA), will be assessed and followed in the same way as PD subjects, allowing for a seamless examination of the prediagnostic and early disease stages of PD." (PMID 26848171, 2016). "On the other hand, the TG mouse expressing I2020T LRRK2 in the olfactory bulb had a sense of smell similar to that of control mice, whereas the Sagamihara patients show a degree of olfactory dysfunction ranging from slight impairment to anosmia." (PMID 22534020, 2012). "Hyposmia/anosmia is often seen in SNCA, GBA and LRRK2 carriers." (PMID 34992521, 2021).